EGR3 (early growth response 3)
Diseases named in the same sentence as EGR3 in open-access papers (continued):
Sharing a sentence is not in itself a finding about the gene and the disease.
heart failure (1 paper, 2024). Inability of the heart to pump blood at an adequate rate to meet tissue metabolic requirements. "This complete lack of AV valves results in severe retrograde blood flow and leads to heart failure and impaired peripheral circulation; egr3 mutants no longer display cardiac output by 96 hpf." (PMID 38748804, 2024).
insomnia (1 paper, 2018). A sleep disorder characterized by difficulty in falling asleep and/or remaining asleep. "Druggable downstream targets of Egr3, including the 5HT2a receptor, may prove useful in combatting sleepiness or insomnia." (PMID 30158860, 2018).
Intellectual disability (1 paper, 2022). "Identifying CaMKIV/EGR3/BDNF pathway in the hippocampal neurons in the context of CH will benefit the drug development of intellectual disability caused by CH." (PMID 36473844, 2022).
ischemia (1 paper, 2014). A hypoperfusion of the BLOOD through an organ or tissue caused by a PATHOLOGIC CONSTRICTION or obstruction of its BLOOD VESSELS, or an absence of BLOOD CIRCULATION. "Previous studies have shown that the quantification of amplified Egr3 fragments leads to a significant increase in expression following 3 h of ischemia, with a maximum increase (5-fold) at 24 h in a mouse survival model of ischemia." (PMID 24886494, 2014). "Moreover, the expression of Egr1 and Egr3 was induced by ischemia." (PMID 24886494, 2014).
lymphoid neoplasm (1 paper, 2021). A neoplasm composed of a lymphocytic cell population which is usually malignant (clonal) by molecular genetic and/or immunophenotypic analysis. "The expression was significantly differential across various types of lymphoid neoplasms for HELQ/EGR3/ZNF667." (PMID 33485349, 2021). "Moreover, HELQ, EGR3 and ZNF667 were expressed differentially among diverse types of lymphoid neoplasm." (PMID 33485349, 2021).
mastocytosis (1 paper, 2017). A clonal myeloproliferative neoplasm characterized by the proliferation and accumulation of neoplastic mast cells in one or multiple organs or organ systems. "Thus, further studies are needed to investigate the role of MAPK/ERK and EGR3 in the pathogenesis of mastocytosis and the development of resistance to KIT inhibition in more details." (PMID 29088753, 2017).
metastatic prostate carcinoma (1 paper, 2021). A carcinoma that arises from the prostate gland and has spread to other anatomic sites. "Recently, the under-expression of EGR3 is demonstrated to be an independent risk factor for metastatic prostate cancer." (PMID 33485349, 2021).
mood disorder (1 paper, 2017). A cognitive disorder a disturbance in which the person's mood is hypothesized to be the main underlying feature. "Egr-3, which colocalizes with Egr-1 and is also induced in an activity-dependent manner, has recently been implicated in multiple mood disorders." (PMID 28503137, 2017).
neuropathies (1 paper, 2010). "EGR3 was also linked to myelination in Schwann cells, hence dysregulation of these concerted pathways may have consequences for neuropathies." (PMID 21152067, 2010).
Obesity (1 paper, 2024). Accumulation of substantial excess body fat. "In this research, we attempted to find the relationship between EGR3 abnormalities caused by circadian disorders in night shift nurses and related obesity, and tried to provide a suitable solution to alleviate the metabolic abnormalities caused by circadian disorders." (PMID 38467615, 2024). "In the present study, firstly we identified that EGR3 can function as a cortisol-dependent peripheral clock gene, and we proved that EGR3 can inhibit adipogenesis in vitro, which can explain the continuous high cortisol in plasma causing abnormal obesity." (PMID 38467615, 2024). "In general, we conclude EGR3 is a peripheral circadian rhythm biomarker for adipogenesis, which can help relieve metabolic disorders caused by shift work, and EGR3 can be a potential target for the abnormal obesity caused by continuous high cortisol in plasma." (PMID 38467615, 2024). "EGR3 is the only rhythmically variable gene in VATs between the shift nurses, and so, we conclude that EGR3 may be responsible for causing obesity induced by shift work." (PMID 38467615, 2024). "Our results may explain that adipogenesis and obesity were caused by disorder rhythm secretion of cortisol via negatively regulated EGR3." (PMID 38467615, 2024). "To confirm, we transfected EGR3 shRNA or overexpression plasmid to hADSCs and 3T3-L1, and found that EGR3 could negatively regulate adipogenesis, which partially explained cortisol can cause abnormal obesity." (PMID 38467615, 2024). "We supposed that EGR3 may be the biomarker in the process of obesity caused by rhythm disturbances." (PMID 38467615, 2024). "This can also prove that EGR3 can work as an important regulator of rhythm disturbance leading to the development of obesity, which can inhibit adipogenesis through HDAC6." (PMID 38467615, 2024). "Our results support that EGR3 may has a physiological role in the function of the peripheral circadian rhythm system and EGR3 may be a potential suppressor of obesity." (PMID 38467615, 2024).
pancreatic cancer (1 paper, 2023). "Its impact on downstream target genes like E2F3, EFNA3, GIT2, MNT, ZNF462, HOXA9, and EGR3 underscores its significance in shaping the aggressive phenotype of pancreatic cancer cells." (PMID 38132457, 2023).
pulmonary fibrosis (1 paper, 2014). Chronic progressive interstitial lung disorder characterized by the replacement of the lung tissue by connective tissue, leading to progressive dyspnea, respiratory failure, or right heart failure. "In this report we demonstrate an increase in morbidity and mortality in Egr3 TG mice using a model of lung fibrosis." (PMID 24475259, 2014). "We show here that these Egr3-induced γδT cells function similarly to wildtype γδT cells, in that they produce Th17-polarizing cytokines, are capable of skewing CD4+ T cells to a Th17 phenotype, and can promote inflammatory disease in a model of pulmonary fibrosis." (PMID 24475259, 2014).
systemic anaphylaxis (1 paper, 2021). "Therefore, Egr3 may increase expression levels of IL-6 and IL-8 during anaphylaxis via NF-κB." (PMID 34234781, 2021). "Egr3 was necessary for passive cutaneous anaphylaxis (PCA) and passive systemic anaphylaxis (PSA)." (PMID 34234781, 2021).
temporal lobe epilepsy (1 paper, 2024). A localization-related (focal) form of epilepsy characterized by recurrent seizures that arise from foci within the temporal lobe, most commonly from its mesial aspect. "EGR3 expression is elevated in the hippocampus in human and animal models with temporal lobe epilepsy." (PMID 38383918, 2024).
Tinnitus (1 paper, 2023). Tinnitus is an auditory perception that can be described as the experience of sound, in the ear or in the head, in the absence of external acoustic stimulation. "The expressions of Fos (p < 0.05), Nr4a1 (p < 0.01), Nr4a3 (p < 0.05), Egr2 (p < 0.01), and Egr3 (p < 0.05) were significantly decreased in the tinnitus group compared to the non-tinnitus group." (PMID 37190538, 2023).
Tremor (1 paper, 2022). An unintentional, oscillating to-and-fro muscle movement about a joint axis. "The tremor strain is characterized by increased expression (in comparison to wild type) of the Egr3 (early growth response protein 3) gene, which encodes a transcription factor controlling the expression of GABAA and NMDA receptors." (PMID 36428502, 2022).
tumor (40 papers, 2010 to 2025). "EGR3 emerged as a pivotal tumor suppressor: its expression inversely correlated with tumor stage and positively associated with CD8+ T cell infiltration." (PMID 41472745, 2025). "A comprehensive bioinformatics study revealed that EGR3 expression is altered across multiple cancers and correlates with immune infiltration, tumor mutational burden, and clinical prognosis." (PMID 40649712, 2025). "The EGR3 gene has been implicated as a tumor suppressor and prognostic marker in certain types of cancer." (PMID 38543002, 2024). "Loss or inactivation of either EGR3 or RGS6 correlates with a more aggressive tumor cell phenotype in multiple cancers, including GBM." (PMID 39796709, 2024). "Functionally, EGR3 has been implicated in the suppression of tumor initiation and progression." (PMID 38338065, 2024). "We next tested whether PS exposure in tumours was dependent on Eiger, and observed an almost complete loss of cell-surface PS in dlg;egr3 tumours." (PMID 31358113, 2019). "Pan-cancer expression profiling revealed significant downregulation of EGR3 in tumor tissues compared to normal counterparts, with progressive reduction across advancing tumor stages." (PMID 41472745, 2025). "Functional studies demonstrated EGR3 overexpression suppressed tumor growth and activated CD8+ T cells." (PMID 41472745, 2025). "High EGR3 expression was also associated with poor survival in MGMT-methylated patients, implicating EGR3 in tumor progression and potentially in cell migration." (PMID 40649712, 2025). "Pan-cancer transcriptomic analyses further reinforce the importance of tumor context in determining EGR3 function." (PMID 40649712, 2025). "To determine if EGR3 expression directly augments T cell effector function, we performed a tumor cell-PBMC co-culture assay." (PMID 41472745, 2025). "Although EGR3 was reported as downregulated in tumor tissues, high EGR3 expression correlated with shorter recurrence-free survival, again suggesting a functional role in disease progression." (PMID 40649712, 2025). "In future work, in vivo models—such as orthotopic xenografts or genetically engineered mouse models—will be essential to evaluate the impact of EGR3 modulation on tumor growth, invasion, and therapeutic response within the native brain microenvironment." (PMID 40649712, 2025). "Collectively, these findings underscore that EGR3 function is shaped by a convergence of tumor-intrinsic and -extrinsic factors—including genetic alterations, transcriptional networks, hormonal cues, and microenvironmental signals." (PMID 40649712, 2025). "Functional studies in 4T1 murine models demonstrated EGR3 overexpression significantly inhibited tumor proliferation and suppressed migratory capacity." (PMID 41472745, 2025). "We further validated the tumor‐suppressive ability of the EGR3 gene in vivo and through clinical study." (PMID 38973154, 2024). "Immune surveillance mediated by T cells is crucial in regulating tumor growth, and EGR3 plays a dynamic role in regulating the proliferation and survival of effector T cells while controlling excessive inflammation." (PMID 38338065, 2024). "We analyzed the significantly upregulated genes in TDECs related to tumor growth factors and selected Angpt2, Lama4, Egr1, Egr3, and Vegfa." (PMID 39440923, 2024). "Further study is required to investigate the expression of EGR3 in clinical patients and analyze its correlation with tumor histological grading and prognosis." (PMID 38338065, 2024). "This indicates that EGR3 participates in tumor initiation and progression through its involvement in inflammatory effector pathways." (PMID 38338065, 2024). "Myeloperoxidase (Mpo), an indicator of neutrophil activity, was downregulated, as was early growth response 3 (Egr3), a gene with tumour suppressor functions." (PMID 38031171, 2023). "The majority of the tumor cells were in the intermediate state, which was governed by the EGR3, NFATC2, and SOX6." (PMID 35903095, 2022).
tumor (continued). "Based on TCGA normal and GTEx database, the expressions of these genes in PC were analyzed, and the levels of PEG10, TFAP2A and EGR3 was remarkably greater in tumor compared to normal group (P <0.01)." (PMID 36284637, 2022). "The promoter region of ZFP36 was bound by EGR3 and transcriptionally activated, thereby exerting a tumor-suppressive effect." (PMID 35538543, 2022). "Compared to normal samples, the expression of E2F2, FOXJ1, EMX1, PAX7, NKX6-1, FOXD1, and ZNF552 was significantly higher (P < 0.05) and the expression of MSX1, STAT4, NR3C2, and EGR3 was significantly lower in tumor samples (all P < 0.05)." (PMID 33688372, 2021). "As expected, the results showed that EGR3 was significantly downregulated in tumor tissues compared with non-tumor tissues (p = 0.0002)." (PMID 34722264, 2021). "Note worthily, silencing of EGR3 reversed the anti-tumor effect of miRNA-210 inhibitor on HepG2 and HepG2.2.15 cells." (PMID 32138690, 2020). "The experimental results of nude mouse models showed that the expression of FasL in xenograft tumor tissues with high expression of EGR3 was also significantly increased." (PMID 32075046, 2020). "Silencing of EGR3 reversed the anti-tumor effect of miRNA-210 inhibitor on HepG2 and HepG2.2.15 cells (P < 0.05)." (PMID 32138690, 2020). "We found an increase in EGR3 protein expression in migrating tumour cells in the periphery, suggesting that EGR3 plays a role in tumour cell migration, thereby indirectly causing accelerated tumour progression, which leads to poor patient outcome." (PMID 32518380, 2020). "For both normal and tumor samples, the predominant anti-Egr3 staining pattern was uniformly epithelial." (PMID 23342084, 2013). "We found that Egr3 has a γj value for tumor cells of -1.96 (p = 0.023), indicating that Egr3 mRNA expression in tumor cells is negatively correlated with relapse status, and this is statistically significant." (PMID 23342084, 2013). "The most important findings suggested that IGF1, IL1α, SHKBP1, and EGR3 were able to distinguish between controls and primary tumor-bearing patients." (PMID 24282616, 2013). "Egr3, for example, is strongly expressed in epithelial tumor cells but not in other stromal cells, therefore observed changes in expression in tumor tissue reflect mostly changes in tumor cells." (PMID 23342084, 2013). "The resultant Egr3 staining intensity values from all 10 areas for tumor and stroma were normalized separately." (PMID 23342084, 2013). "Anergy is a hyporesponsive state of T cells commonly encountered at tumor vicinity that is mediated by poor co-stimulation in absence of IL-2, a condition that upregulates various anergy related genes cbl-b, egr2, egr3, itch, GRAIL and DGK1α in T cells." (PMID 23785504, 2013). "This mechanistic diversity necessitates careful delineation of EGR3′s role in each tumor setting." (PMID 40649712, 2025). "These factors may determine whether EGR3 functions as a transcriptional activator or repressor of oncogenic or tumor-suppressive targets." (PMID 40649712, 2025). "Emerging evidence from other tumor types supports the highly context-dependent function of EGR3." (PMID 40649712, 2025). "First, the cellular context, including differences in cell type, genetic background, and tumor microenvironment, may influence EGR3′s functional role." (PMID 40649712, 2025). "In vivo xenograft experiments revealed 56.7% tumor volume reduction with EGR3 overexpression." (PMID 41472745, 2025). "Differences in tumor subtype, cellular origin, epigenetic regulation, or the local tumor microenvironment may all influence EGR3 function." (PMID 40649712, 2025). "To determine whether the anti-tumor effects of C6 ceramide are correlated with EGR3, we conducted qPCR and Western blotting analyses to confirm this hypothesis." (PMID 38338065, 2024). "Notably, EGR3 has been found to play a significant role as a tumor suppressor and prognostic marker in different types of cancer." (PMID 38543002, 2024).
tumor (continued). "Additionally, it reveals that the target gene of C6 ceramide, EGR3, can effectively exert anti-tumor effects by regulating the JAK1/STAT3 signaling pathway." (PMID 38338065, 2024). "EGR3 has been shown to be involved in a number of cancers and in the regulation of the immune response, and this gene has recently been linked to HCC when it was used to inhibit the growth of tumor cells." (PMID 32424123, 2020). "To further assess whether Egr was required for Defensin-induced tumour cell death, we injected synthetic Defensin peptide into control, dlg or dlg;egr3 mutant larvae." (PMID 31358113, 2019). "EGR3′s activity is also shaped by co-regulatory proteins, such as other transcription factors or chromatin modifiers, which may differ in abundance or interaction patterns across tumor models." (PMID 40649712, 2025). "Finally, to further test the hypothesis that Def requires PS to bind to tumours, we assessed the ability of overexpressed Def-HA to bind to dlg,egr3 mutant tumours." (PMID 31358113, 2019). "We found that EGR3-overexpressing tumor cells significantly boosted the proportion of cytokine-producing CD8+ T cells, indicating a potent role for EGR3 in promoting T cell activation." (PMID 41472745, 2025). "The 12 downregulated genes were functionally involved in 8 pathways, including tumor maker (TP63, MMP9, and EGR3 genes) and antigen processing (HLA-F-AS1 and HLA-A genes)." (PMID 35915657, 2022). "As revealed from the results, lower EGR1, EGR2, and EGR3 levels displayed a relationship to higher SBR grade, NPI, and tumor stage, respectively (p < 0.0001)." (PMID 33614706, 2020). "EGR3, an important member of the EGR family, is known as a suppressor of tumor initiation and progression." (PMID 32138690, 2020). "However, the observed cytoplasmic EGR3 expression may have several functional implications; first it could indicate that tumour cells with this expression pattern have a high synthesis of EGR3 protein within the endoplasmatic reticulum, where it accumulates prior to nuclear translocation." (PMID 32518380, 2020). "The protein profiles of nine targets, namely IGFBP2, IGF1, SHKBP1, ETS1, IL1α, STX2, MAML3, EGR3 and XIAP were verified as significant contributors to tumor classification." (PMID 24282616, 2013). "Similarly, after their culture with ECs, IL30-overexpressing PCs showed a dramatic upregulation of a wide range of oncogenes, which included CCND2, EGR3, IGFBP5, KLK3, PDLIM4, PTGS1 and SHBG and a few tumor suppressors, such as GPX3, FOXO1, MAX and NKX3-1." (PMID 38087324, 2023). "Furthermore, the most effective analogs were analyzed via qPCR to determine efficacy in modulating expression of two critical tumor suppressor genes, ATF3 and EGR3." (PMID 37947652, 2023). "The mean fraction of EGR3 + tumour cells did not change significantly across the different tumour regions (central = 10.6%, intermediate = 8.2%, periphery = 8.5%)." (PMID 32518380, 2020). "Notably, tumor-suppressive roles have been reported for CAMK2B, EGR3, NPAS2, PCDH8, and RGS6." (PMID 39796709, 2024). "We showed that the expression of EGR1, EGR2, EGR3, and EGR4 was significantly lowered in HCC specimens in comparison to nontumor specimens, which suggested that members of the EGR family may serve as a tumor suppressor in the progression of HCC." (PMID 36046377, 2022). "In addition to the 14 probe sets with a significant negative γj value, another 12 probe sets have a γj tumor with p-value ≤0.1, indicating that Egr3-correlated genes tend to show higher expression in non-relapse than in relapse tumor samples." (PMID 23342084, 2013). "Indeed, of the 54,000 probe sets of the U133plus2 array, Egr3 exhibits the 40th most negative γj tumor value observed." (PMID 23342084, 2013).
tumor (continued). "Analysis of Egr3 mRNA expression in relation to the relapse status reveals that Egr3 mRNA expression is increased in tumor cells of non-relapsed samples (n = 63) compared to normal prostate cells, but is significantly lower in relapsed samples (n = 38) compared to non-relapse." (PMID 23342084, 2013). "Egr3 (probe set 40375_at) exhibits the same pattern as was seen in the SPECS data set where expression was low in normal donor prostate tissue, increased in tumor-adjacent normal tissue, increased in primary prostate tissue, and decreased in metastatic samples." (PMID 23342084, 2013).